SYP (synaptophysin)
Diseases named in the same sentence as SYP in open-access papers (continued):
Sharing a sentence is not in itself a finding about the gene and the disease.
tumor (continued). "Immunohistochemically, this resected specimen revealed that the tumor was positive for synaptophysin, chromogranin A, CD56, and ACTH; the Ki-67-labeling index of the tumor cells was 2.7%." (PMID 41464537, 2025). "Re-biopsy of the primary lesion identified that most of the tumor cells were CD56 and synaptophysin positive." (PMID 39456595, 2024). "The tumor was positive for cytokeratin AE1/AE3, carcinoembryonic antigen, synaptophysin, chromogranin, thyroid transcription factor 1 (TTF-1), S-100, and calcitonin." (PMID 39553134, 2024). "The tumor was diffusely positive for glial markers (GFAP and OLIG2) and there was widespread expression of synaptophysin." (PMID 38650040, 2024). "The immunohistochemistry (IHC) studies performed showed the tumor was positive for CKA1AE3, chromogranin, synaptophysin, and focal positivity for insulin." (PMID 39104820, 2024). "Following this cycle, the patient demonstrated significant improvement in cell counts; however, minimal residual tumor cells remained, evidenced by the presence of rare scattered CD56, chromogranin, and synaptophysin-positive cells." (PMID 39677122, 2024). "Immunohistochemical analysis of tumor cells revealed the following results: AE1/AE3(+), TTF-1(–), p40(–), chromogranin A(–), synaptophysin(–), CD56(–), INSM1(–)." (PMID 39463789, 2024). "Immunohistochemical stains demonstrate the tumor cells to be strongly positive for vimentin, pankeratin, CK7, CK20, chromogranin, synaptophysin, CD45, and focally positive for CD56." (PMID 38933829, 2024). "The tumor is positive for pancytokeratin and variably positive for CK5/6, p63/p40, and CK7; focal reactivity for synaptophysin and chromogranin is evident." (PMID 38315310, 2024). "The tumor consisted of round cells mimicking a neuroendocrine neoplasm (NEN), with positive staining for synaptophysin and CD56." (PMID 39439633, 2024). "The tumor cells were positive for glial markers (GFAP, OLIG2) and markers of neuronal differentiation (synaptophysin, chromogranin) were focally expressed within the tumor." (PMID 38650040, 2024). "SMARCA4 expression was positively correlated with multiple NE genes including SYP, CHGA, INSM1, DLL3 and NCAM1 and negatively correlated with non-NE factors REST, NOTCH2, and YAP1 in both SCLC cell lines and patient tumor databases." (PMID 39080761, 2024). "We further validated the expression of Chromogranin A, Synaptophysin, PAX6 and NCAM1 using immunohistochemistry staining on MAP model tumor sections." (PMID 38609433, 2024). "The preliminary diagnosis was CNS embryonal tumor, NOS, supported by morphology and its strong synaptophysin immunoreactivity." (PMID 38926750, 2024). "The tumor cells were characterized based on their IHC reactivity to cytokeratin (AE1/AE3 or CAM 5.2) and neuroendocrine markers, including CgA, synaptophysin, and CD56." (PMID 37867522, 2023). "GI NEC often diffusely expresses neuroendocrine markers, including chromogranin, synaptophysin and CD56, and tumor cells express epithelial markers." (PMID 38090508, 2023). "SCLC is the most common form of neuroendocrine lung cancer and produces the classic neuroendocrine markers, Chromogranin A, synaptophysin, NCAM (CD56) and Calcitonin gene-related peptide (CGRP), which are commonly used as SCLC tumor markers." (PMID 37608896, 2023). "The classic neuroendocrine markers (synaptophysin, chromogranin A, and NCAM) are usually used for diagnosis of the tumor biopsy sample and the cisplatin-etoposide combination is used as standard first line chemotherapy." (PMID 37608896, 2023). "Immunohistochemical staining showed that the tumor cells were positive for CD56, synaptophysin, and chromogranin A." (PMID 37878146, 2023). "Some reports described patchy staining of synaptophysin, p16, or even TTF-1 and tumor EBER-negative status." (PMID 38239638, 2023).
tumor (continued). "Immunohistochemical staining showed that tumor cells were positive for CD56, synaptophysin, and chromogranin A. Twenty-three days after the CT-guided PTNB, repeat CT scan showed that the tumor size regressed to 0.6 × 0.6 cm." (PMID 37878146, 2023). "In the tumor tissues of NEPC patients, AR signaling is low or lost, and such typical NE markers as neuronal-specific enolase 2 (ENO2), synaptophysin (SYP), NCAM1 and chromogranin A(CHGA) are remarkably elevated." (PMID 37563661, 2023). "Further, analysis of IHC staining across all tumor sections showed a positive correlation between the intensity scores of CXCR7 and SYP, CXCR7, and CHGA." (PMID 37347559, 2023). "The routinely used immunochemical markers CgA, synaptophysin and CD56 have limitations of being single analytes and their presence in non-tumour tissue." (PMID 36362433, 2022). "Tumor cells expressed Collagen type IV, α-smooth muscle actin (α-SMA), and synaptophysin in most cases." (PMID 36699621, 2022). "Immunohistochemically, the tumor was positive for chromogranin A, CD56, and synaptophysin, and a diagnosis of paraganglioma of the urinary bladder was confirmed." (PMID 35676716, 2022). "Having determined that synaptophysin and, to a lesser extent, tyrosine hydroxylase are useful chromaffin cell markers in PPGL tumour cultures, we assessed the expression of these and other markers in a selection of short and long-term cultures." (PMID 36178902, 2022). "Six SCNEC cases and two UC cases from the external cohort were immunostained for synaptophysin, CD117, and GATA3 using whole tumor sections in our institution." (PMID 35626098, 2022). "Markers CD24, CD44, PDX1, synaptophysin, CD49, CDX2, CD45, DAXX, PCAD and CK7 had lower expression in the tumour relative to that in the non-tumour with the exception of one patient." (PMID 36362433, 2022). "The neuroendocrine markers: Neuron Specific Enolase (NSE), chromogranin A, synaptophysin and CD56 were expressed in 100% of the tumor specimens in which they were tested." (PMID 35528006, 2022). "Synaptophysin (64.3%) and CD56 (71%) have higher sensitivity than chromogranin A (29%) in the tumor differentiation." (PMID 35804996, 2022). "Previous studies have shown that immunohistochemical analysis is superior to routine H&E assessment and it is recommended to use at least three immunohistochemical markers such as synaptophysin, chromogranin, PGP 9.5 and cyclin-D1 to demonstrate tumor tissue." (PMID 34558657, 2022). "Labeling for synaptophysin and TPO was weak and only a few tumor cells showed immunopositivity for synaptophysin." (PMID 35681825, 2022). "In G2, CD56, CgA, NSE, vimentin and Ki-67 were higher in tumour tissue compared to those in non-tumour, and levels of CD44, CD45, CK7, DAXX, synaptophysin and PDX1 were lower in tumour tissue relative to those in non-tumour tissue." (PMID 36362433, 2022). "In our case, the tumor cells are strongly positive for cytokeratin (AE1/AE3) and INSM1, and scatteredly positive for chromogranin A, synaptophysin, and CD56." (PMID 34477164, 2021). "In the glioneuronal components, the astrocyte‐like tumor cells were positive for GFAP and the neurocyte‐like tumor cells were positive for synaptophysin." (PMID 33576087, 2021). "The neoplasm was mainly composed of round, uninucleate cells with hyperchromatic nuclei, which were immunopositive for OLIG2, doublecortin, MAP2, synaptophysin, and vimentin, indicating components of both oligodendroglial and neuronal differentiation." (PMID 34977226, 2021). "The neuroendocrine origin of the tumor spheroids was confirmed by immunoblotting analysis of neuroendocrine biomarkers: chromogranin A (CgA), somatostatin receptor 2 (SSTR2), and synaptophysin (SYP)." (PMID 34065268, 2021). "Immunohistochemical staining with synaptophysin, chromogranin A, and CD56 was confined to the tumor." (PMID 33388069, 2021).
tumor (continued). "Histological and immunoblot analysis revealed small round blue cell tumours poor in stroma that expressed NCAM1, synaptophysin (SYP), Chromogranin A (CGA) and MYCN in Rosa26_Alkal2;Th‐MYCN tumours, in agreement with NB." (PMID 33411331, 2021). "The markers synaptophysin, PCNA, DAXX, laminin and CD14 had similar expression levels in tumour and non-tumour tissue." (PMID 33906633, 2021). "Immunohistochemical staining revealed that the tumor expressed chromogranin A, NSE and synaptophysin." (PMID 32569235, 2020). "Immunofluorescence of 30 NET G3/NEC patients showed overall varied expression of synaptophysin, CD45, and CD68 as expected with such heterogenous tissues derived from distinct tumor sites, morphologies, and disease stages." (PMID 33228231, 2020). "Immunohistochemical staining of chromogranin A, synaptophysin, and CD56 suggested that the tumor was a GB-NET." (PMID 33108599, 2020). "Immunohistochemical tests were performed and tumour demonstrated diffuse positivity for CD99, ERG, CD56 and focal positivity for Synaptophysin, PanCK, Cam5.2." (PMID 32450834, 2020). "Regions of interest (ROI) were selected based on Ki67 positivity (tumor-enriched regions) and immunofluorescence imaging of CD45, CD68, and tumor marker synaptophysin expression to scan tumor regions." (PMID 33228231, 2020). "Well in line with histology, the tumor showed expression of both glial (e.g. GFAP) and neuronal markers (e.g. synaptophysin) with pathological expression of CD34 and retained ATRX expression." (PMID 32451719, 2020). "Immunohistochemically, the tumor cells were positive for hepatocyte paraffin 1, AE1/AE3, and CD10 and negative for AFP, progesterone receptor, vimentin, chromogranin A, and synaptophysin." (PMID 31784920, 2019). "Histopathologcal examination of the resected tumor confirmed the diagnosis of PGL with positive chromogranin A and synaptophysin stains and a Ki67 proliferation index of 3%." (PMID 31666924, 2019). "Staining with synaptophysin, the IHC marker for NB32, identified tumor dissemination to the liver, lungs, and kidney." (PMID 31409909, 2019). "The stained tumours in the untreated control group showed a high and specific expression of MTC markers chromogranin A, synaptophysin, and calcitonin, and were morphologically consistent with MTC." (PMID 31725814, 2019). "The resected tumor was pathologically similar to the primary lung LCNEC and staining of the tumor was positive for chromogranin A and synaptophysin." (PMID 31678698, 2019). "Tumor cells were positive only for cytokeratin AE1/AE3, and negative for cytokeratin 5/6 and 7, p63, SMA, PS100, chromogranin, and synaptophysin." (PMID 29489937, 2018). "Immunohistochemical staining showed that almost all tumor cells were positive for CD56, synaptophysin, and chromogranin A. Ki67 was detected in 15–20% of the tumor cells." (PMID 29052535, 2017). "Immunohistochemically, the neuroendocrine markers chromogranin A, synaptophysin, and NSE were limited to the NEC component of the primary tumor." (PMID 28248881, 2017). "Levels of NE cancer markers, which include aschaete-scute homolog 1 (ASCL1), synaptophysin (SYN), and chromogranin A (CgA), correlates with tumor burden." (PMID 29050323, 2017). "After resection, the tumor’s histology and immunohistochemistry (positive for CD99, vimentin and synaptophysin) results suggested ES/PNET." (PMID 28472972, 2017). "We also analyzed circulating tumor cells (CTCs) from patients with PDA for neuroendocrine marker expression and found co-staining of CK and SYP in 4 of 5 patients assessed with a frequency ranging from 30 to 66%." (PMID 29170413, 2017). "The tumor was positive for vimentin, CD10, α1-antichymotrypsin, α1-antitrypsin, β-catenin, neuron-specific enolase, synaptophysin, and progesterone receptor." (PMID 30631811, 2016).
tumor (continued). "A case with a histopathologic finding of small round cells with scant cytoplasm should be evaluated for synaptophysin, chromogranin A, and CD56 expression, followed by ultrastructural analysis to detect neurosecretory granules in the tumor cells." (PMID 27818885, 2016). "Immunohistochemically tumor cells are positive for cytokeratin, estrogen receptors (ER), progesterone receptors (PR), neuron specific enolase (NSE), chromogranin A, and/or synaptophysin." (PMID 27840759, 2016). "The tumour cells show immunoreactivity to a range of keratins including AE1/AE3, keratin 7, and neuroendocrine markers such as chromogranin and synaptophysin." (PMID 27429819, 2016). "To ensure that our xenograft models retained typical features of their respective subtype, we assessed expression of molecular markers specific to PCa (AR, PSA) and NEPC (SYP, CHGA) in the investigated Living Tumor Lab (LTL) tumor lines." (PMID 25859291, 2015). "In contrast, SYP immunoreactivity was strictly restricted to LTL331R, in line with the expected histological profiles of each tumor line." (PMID 25859291, 2015). "Immunohistochemically, the tumor cells were diffusely positive to CK7, CEA, GCDFP-15, synaptophysin, estrogen and progesterone receptors." (PMID 26055980, 2015). "Tumor cells were positive for periodic acid-Schiff (PAS) reaction and immunoreactive for CD99, NKX2.2 and the neuroendocrine markers CD56 and synaptophysin." (PMID 25608963, 2015). "Cords and nests of small round tumor cells, marked by CD56 and synaptophysin, were also seen in bone marrow from the iliac crest bone." (PMID 26039124, 2015). "This tumour entity is currently assessed by immunohistochemistry (IHC) detecting “general” NE markers such as chromogranin A (CHGA) and synaptophysin (SYP), but other markers have been considered as well." (PMID 24277232, 2014). "Synaptophysin was focally expressed in 1/24 carcinomas, notably this positive case was an ILC with moderate staining in <10% of tumor cells." (PMID 24701575, 2014). "Microscopically, there was an infiltrated lymph node along one edge, and the mass consisted of sheets of poorly-differentiated metastatic tumor cells positive for GFAP and rarely for synaptophysin." (PMID 25563358, 2014). "The small epithelioid areas of tumor had strong diffuse immunoreactivity for S100, CD56, and synaptophysin, with lesser GFAP immunostaining, estimated at 1/5 of the small epithelioid cells." (PMID 24321241, 2014). "The tumor stained positively for MIC-2, synaptophysin, neuron-specific enolase (NSE) and neurofilament antibodies." (PMID 24959242, 2014). "The tumor comprised small, round-to-oval nuclei and stained positively for MIC-2, synaptophysin, neuron-specific enolase and neurofilament antibodies." (PMID 24959242, 2014). "Immunohistochemistry was diffusely positive for synaptophysin and MIB-1 was positive in 5–10% of tumor cells." (PMID 25258691, 2014). "Immunohistochemical staining was positive for synaptophysin, NSE, CK7, and ER in almost all the tumor cells; however, PgR was positive only focally." (PMID 23738176, 2013). "Most of the tumor cells were found to have a positive reaction for pan-cytokeratin, CK7, TTF1, chromogranin A and synaptophysin." (PMID 23119202, 2012). "The tumor showed characteristic features of pPNET with pseudo-rosettes, positive IHC for the MIC-2 gene and synaptophysin and ultrastructral finding of neurosecretory granules." (PMID 19700881, 2009). "Tumor cells were diffusely immunopositive for calcitonin, HMB-45, chromogranin, synaptophysin, CEA but showed focal paranuclear dot positivity for cytokeratin." (PMID 18190715, 2008). "Immunohistochemically, the tumor cells were negative for chromogranin, synaptophysin, and INSM-1 but positive for beta-catenin, CD56, and multifocally for S100." (PMID 41869246, 2026).
tumor (continued). "The IHC staining was positive for CD99 and FLI-1 (in >50% of tumor cells) and negative for AE1/AE3, INI-1 loss, WT1, desmin, myogenin, BCOR, TLE-1, CD45CLA, and synaptophysin." (PMID 41230381, 2026). "The diagnosis of LCNEC is established through neuroendocrine morphological features and immunohistochemical detection of at least one neuroendocrine marker CD56, synaptophysin, or chromogranin A in no less than 10% of tumor cells." (PMID 41153253, 2025). "Being neoplasms of neuroendocrine nature, SCCOPT and ovarian metastases from SCC both show positive immunohistochemistry for typical neuroendocrine markers such as NSE, synaptophysin, CgA, and CD56." (PMID 41464736, 2025). "While most MCC show strong staining with neuroendocrine markers, our tumor only exhibited regional focal staining for synaptophysin, INSM1, and CD56 and lacked chromogranin expression entirely." (PMID 40640075, 2025). "In the early stages, organoids were able to retain differentiated chromaffin cells, as indicated by metanephrine levels in culture supernatants that initially mirrored primary tumor patterns, as well as the expression of differentiation markers such as CHGA, SYP, and PNMT." (PMID 40576438, 2025). "The tumor was evaluated with immunohistochemical stains and found to be positive for synaptophysin and Lu-5 and negative for chromogranin." (PMID 41458666, 2025). "Immunohistochemistry showed the tumor cells were diffusely positive for synaptophysin and chromogranin, negative for p40, and focally positive for somatostatin in approximately 5% of tumor cells." (PMID 40336855, 2025). "Calcitonin gene-related peptide (CGRP)-positive, substance P (SP)-positive and SYP-positive fibres were also profusely present near, but not within, tumours." (PMID 40931078, 2025). "Synaptophysin, chromogranin A, and CD56 are commonly used markers to identify NE differentiation and the non-NE markers include caudal-type homeobox 2 (CDX2), cytokeratin 7 (CK7), CK20, among others depending on the specific neoplasm." (PMID 41041158, 2025). "Additional markers like MSA, CEA, SMA, synaptophysin, CD57, and S100 may also be variably expressed, reflecting the tumor’s heterogeneous differentiation." (PMID 40315807, 2025). "Univariate analysis did not identify a statistically significant relationship between DFS and variables including age, gender, smoking history, tumor localization, TTF-1, P40, chromogranin A, synaptophysin, adjuvant chemotherapy, adjuvant radiotherapy, or type of surgery." (PMID 41153253, 2025). "Immunohistochemical (IHC) staining was non-specific for tumor origin, showing positivity for calretinin, weak positivity for synaptophysin and PAX8, and scattered staining for AE1/3, Cam5.2, and EMA." (PMID 40421964, 2025). "The qPCR analysis provided further insights into these findings, revealing a downward trend in the mRNA expression of adrenomedullary markers (CHGA, SYP, PNMT, and TH) in PCC organoids compared to primary tumor tissue, and in adrenomedullary organoids compared to NAM tissue." (PMID 40576438, 2025). "The absence of synaptophysin and chromogranin staining in our case was crucial in distinguishing the tumor from a NET." (PMID 41246713, 2025). "The diagnosis of NEC depends on histopathological recognition and reactivity to neuroendocrine markers such as synaptophysin, cytokeratin, and chromogranin A. The WHO classified tumor activity based on mitotic count and Ki‐67 proliferation index into NET G1, NET G2, NET G3, and NEC." (PMID 39894895, 2025). "Briefly, for all panels, synaptophysin positive (SYN+) status was considered indicative of tumour cells, and the SYN signal was used to delineate the “tumour region” in each sample; SYN− status was indicative of stromal cells and was used to delineate “adjacent normal regions”." (PMID 41285059, 2025). "Nevertheless, SYP-positive cells were scattered in limited tumor nests and appeared to comprise no more than 30% of the entire tumor." (PMID 39937015, 2025).